CRP (C-reactive protein)
Diseases named in the same sentence as CRP in open-access papers (continued):
Sharing a sentence is not in itself a finding about the gene and the disease.
autonomic dysfunction (13 papers, 2013 to 2024). "For example, CRP, and leukocytes were reported to be related to autonomic dysfunction, but more studies reported no such association." (PMID 27165730, 2016). "The results showed that autonomic dysfunction, consciousness declination, ICU admission, WBC, CRP, neutrophil percentage, albumin, and NPAR were statistically significantly different between the two groups (P < 0.05)." (PMID 35479085, 2022). "Cardiac dysfunction and elevated C-reactive protein, but not a reduced HRV as surrogate of autonomic dysfunction, were associated with increased hs-TnT levels in IS patients independent of established cardiovascular risk factors." (PMID 36585640, 2022). "The study also indicated a negative correlation between the inflammatory marker C-reactive protein (CRP) and HRR, suggesting that IR, hyperandrogenism, autonomic dysfunction, and chronic low-grade inflammation may collectively play a role in the pathophysiology of PCOS." (PMID 38313837, 2023). "Moreover, the markers of chronic inFlammation (C-reactive protein) and autonomic dysfunction (norepinephrine levels) that could link CD and IR were not statistically different among the two groups, suggesting a more clear and isolated effect of HF diagnosis." (PMID 32489809, 2020).
diffuse large B-cell lymphoma (13 papers, 2013 to 2024). "A recent meta-analysis of 3000 subjects indicated that higher CRP levels before treatment were associated with poor OS and PFS in diffuse large B-cell lymphoma." (PMID 38172843, 2024). "A recent study showed that elevated CRP was related to decreased 5-year OS in diffuse large B-cell lymphoma patients." (PMID 37460979, 2023). "As a CRP level ≤8.02 mg/L was defined as the normal range in our center, a more recent study from our center used CRP levels >8.02 mg/L as a cutoff value and found that elevated serum CRP levels were significantly associated with a poor prognosis in diffuse large B-cell lymphoma (DLBCL) patients." (PMID 23724031, 2013). "CRP can be a possible prognostic marker for survival in diffuse large B-cell lymphoma (DLBCL) and follicular lymphoma, while generally, notable increases have also been reported in some other non-Hodgkin’s and Hodgkin’s lymphomas as well." (PMID 37873776, 2023). "Fecal calprotectin was found to be elevated to 2,893 ug/g and C-reactive protein was 219 mg/L. Biopsies eventually revealed diffuse large B-cell lymphoma (DLBCL) of the jejunum and focal active colitis with crypt abscess of the ascending colon." (PMID 35923677, 2022). "The C-reactive protein-to-albumin ratio (CAR) has not been assessed in diffuse large B cell lymphoma (DLBCL, the most common non-Hodgkin lymphoma)." (PMID 33514832, 2021). "Therefore, C-reactive protein (CRP) was not evaluated by us although it is an objective inflammation marker and has been found to be a prognostic indicator in diffuse large B-cell lymphoma." (PMID 29853866, 2018). "Objectives and study design: In this population-based study of 602 patients, we amended C-reactive protein (CRP) and plasma albumin (PA) levels around the diagnosis of diffuse large B-cell lymphoma (DLBCL) to the International Prognostic Index (IPI) and assessed 0–90, 91–365, and +365-day survival." (PMID 35238275, 2022).
diverticular disease (13 papers, 2013 to 2025). A complex disorder characterised by mucosal outpouchings (diverticulae) of the colonic wall which can become infected and inflamed leading to diverticulitis, perforation and bleeding. "C-reactive protein (CRP) is a widely recognized biomarker of systemic inflammation and has been frequently used to evaluate the immunomodulatory effects of probiotics in gastrointestinal conditions, including diverticular disease (DD)." (PMID 41517338, 2025). "Because of the importance of inflammation in the pathogenesis of diverticular disease, pro-inflammatory indicators such as C-reactive protein (CRP), erythrocyte sedimentation rate, leukocyte count, fecal calprotectin, and procalcitonin may be possible biomarkers." (PMID 36978310, 2023). "In patients with pre-existing diverticular disease, we should monitor for increased WBC counts and CRP levels after the initiation of treatment with naldemedine, and consider performing appropriate tests early in the event of abdominal complaints." (PMID 39143638, 2024). "High-density lipoprotein cholesterol was lower in patients with more severe forms of diverticulosis (DICA category 2 and 3), while CRP levels were significantly higher (p = 0.006 and p = 0.015, respectively)." (PMID 35056346, 2021).
H1N1 influenza (13 papers, 2010 to 2024). "In the meantime, we found that a higher CRP level was also significantly associated with the severe HAdV infection group, which looks like CRP levels in H1N1 influenza patients who develop a severe disease outcome." (PMID 33145348, 2020). "However, signs of a more serious clinical picture in H1N1 influenza are associated with elevated CRP levels." (PMID 39064460, 2024). "Although this study cannot establish a causal link between higher levels of CRP and severe H1N1 influenza, it may suggest monitoring H1N1 patients with high CRP level upon diagnosis." (PMID 30288556, 2019). "Retrospective observational study including 364 confirmed A/H1N1 flu patients demonstrated CRP<10 mg/dl was independently associated with A/H1N1 etiology, and high levels of CRP was consistently with a severe disease outcome in H1N1 influenza patients." (PMID 34447386, 2021). "CRP levels have been consistently shown to be significantly higher in H1N1 influenza patients who develop a severe disease outcome." (PMID 30288556, 2019). "This study evaluated the diagnostic value of measuring the levels of procalcitonin (PCT) and C‐reactive protein (CRP) to differentiate children co‐infected with H1N1 influenza and bacteria from children infected with H1N1 influenza alone." (PMID 30443990, 2019). "The present study was conducted to systematically evaluate the levels of CRP in patients with H1N1 influenza at different degrees of severity." (PMID 30288556, 2019). "The resuts of the present study suggest that serum CRP can be employed—in combination with other biomarkers—to predict the complications of H1N1 influenza." (PMID 30288556, 2019). "We conducted a comprehensive search in Ovid MEDLINE, Ovid MEDLINE (R) Epub ahead of Print, Embase and Embase Classic to identify human studies reporting measurements of CRP levels in patients infected with H1N1 influenza at various levels of disease severity." (PMID 30288556, 2019). "The aim of this study is to analyze the dynamic fluctuations of T cells, B cells, natural killer (NK) cells, and regulatory T cells in patients infected with novel influenza H1N1, as well as serum cytokines and C-reactive protein (CRP)." (PMID 21569236, 2011). "Studies with regard to the relationship between CRP, oxygen exchange, and H1N1 influenza revealed that oxygen exchange and CRP could predict safe discharge from hospital." (PMID 34447386, 2021). "Further, the small number of studies and their limited geographic region may levy limitations in terms of the ability to generalize the utility of CRP as a marker for severe H1N1 influenza." (PMID 30288556, 2019). "The results of the data analysis show that the average CRP levels upon diagnosis were significantly higher (P < 0.05) in patients who developed severe H1N1 influenza compared to their counterparts with a no severe disease." (PMID 30288556, 2019). "We aim to systematically review and evaluate the levels of CRP in severe and non-severe H1N1 influenza cases and assess its utility as a biomarker in predicting the severity of infection." (PMID 30288556, 2019). "Altered CRP and ESR values were not prominent in 2009 H1N1 virus infections, but higher CRP values were associated with a more severe illness." (PMID 21864391, 2011). "The absence of an agreed protocol for the measurement of serum CRP in patients with H1N1 virus infection admitted to the ED led to the exclusion of 34% of the 315 patients from the study cohort and may have also biased the results." (PMID 20920320, 2010).
Hashimoto thyroiditis (13 papers, 2010 to 2025). An autoimmune disorder caused by the production of autoantibodies against thyroid tissue. "A study published in 2025 confirms a positive correlation between LTB4 and CRP in patients suffering from Hashimoto’s disease (before the gluten–free diet–r = 0.396; after the introduction of the gluten–free diet–r = 0.642)." (PMID 41439954, 2025). "A study published in 2025 involving women suffering from Hashimoto’s Thyroiditis confirmed the existence of positive correlations between CRP and TXB2 (r = 0.04) and PGE2 (r = 0.17)." (PMID 41294849, 2025). "Studies involving patients with chronic lymphocytic thyroiditis also reported an increase in CRP levels compared to a control group of healthy individuals (p = 0.064)." (PMID 41439954, 2025). "The objective of the study was to estimate and compare salivary CRP levels in Hashimoto's thyroiditis and Subacute thyroiditis." (PMID 21151525, 2010). "The objective of the study was to estimate and compare salivary CRP levels in Hashimoto's thyroiditis (HT) and Subacute thyroiditis (SAT)." (PMID 21151525, 2010). "The correlations obtained between AA acid derivatives and CBC and CRP in patients suffering from Hashimoto’s Thyroiditis appear to be significant, especially in the case of 5S-HETE, and 5-oxo-ETE, due to the highest amounts of these acids in the blood of the tested women." (PMID 41439954, 2025). "However, contradictory results have been reported in patients with Graves' disease and Hashimoto's thyroiditis, and IL‐39 showed down‐regulated levels but was positively correlated with two inflammatory markers, CRP and leukocyte count." (PMID 36757903, 2023). "The initial concentration of anti-TPO was lower compared to other studies that also included patients with newly diagnosed and previously untreated Hashimoto’s disease, which may have been partly reflected in the higher levels of CRP in studies by other authors." (PMID 35889825, 2022). "According to a study carried out in Italy, individuals who suffer from both Hashimoto’s thyroiditis and CKD have elevated levels of specific inflammatory markers, including C-reactive protein (CRP) and interleukin-6 (IL-6), when compared to those who only have CKD." (PMID 39004740, 2024). "The most important outcomes of the present study are as follows: (a) the PLR of the subjects with increased Hashimoto’s thyroiditis is significantly higher than the PLR of the control group, and (b) there is a strong positive correlation between the PLR and CRP." (PMID 36810529, 2023).
head and neck squamous cell carcinoma (13 papers, 2015 to 2025). A squamous cell carcinoma that arises from any of the following anatomic sites: lip and oral cavity, nasal cavity, paranasal sinuses, pharynx, larynx, and salivary glands. "CYFRA 21-1 (cytokeratin 19 fragment) and C-reactive proteins (CRP) were separately reported to be associated with prognosis of head and neck squamous cell carcinoma." (PMID 26292957, 2015). "This study evaluated the association of pretreatment serum C-reactive protein (CRP) level with prognosis in patients with head and neck squamous cell carcinoma (HNSCC)." (PMID 35847918, 2022). "The prognostic significance of serum C-reactive protein (CRP) levels has been extensively researched in head and neck squamous cell carcinoma." (PMID 40725739, 2025). "A recent meta-analysis further confirmed that elevated CRP levels independently predict worse overall survival across head and neck squamous cell carcinomas, underscoring the strong link between systemic inflammation and tumor aggressiveness." (PMID 41464825, 2025). "Thus, patients with head and neck squamous cell carcinoma are heterogeneous with regard to the development of an acute phase reaction (i.e., show wide variation in CRP levels), and the induction of an acute phase reaction depends both on clinical/life style and tumor characteristics." (PMID 33066437, 2020). "Because of the significant link between the inflammatory reaction and tumor progression, NLR, PLR, and CRP have been found to have significant prognostic value for predicting survival in diverse cancers including head and neck squamous cell carcinoma (HNSCC)." (PMID 31382679, 2019). "The prognostic role of the C‐reactive protein (CRP) in head and neck squamous cell carcinoma (HNSCC) has not been well investigated." (PMID 33201589, 2020). "C-reactive protein (CRP) has a prognostic impact in head and neck squamous cell carcinoma (HNSCC)." (PMID 33066437, 2020).
renal fibrosis (13 papers, 2016 to 2024). A final common manifestation of a wide variety of chronic kidney diseases characterized by glomerulosclerosis and tubulointerstitial fibrosis. "In kidney disease, overexpression of CRP can cause kidney cell damage and renal fibrosis." (PMID 37102663, 2023). "More tubulointerstitial fibrosis was found in Trichrome-stained kidney sections, quantitative analysis of Sirius red stain, and SMA expression was higher at Day 7 post-IRI in PLC3 mice than LC3 mice, suggesting that CRP mice are more susceptible to develop renal fibrosis after ischemic injury." (PMID 28886014, 2017). "This is also confirmed by deleting Smad3 to inhibit UUO-induced renal fibrosis in CRP transgenic mice." (PMID 35541902, 2022). "CRP can activate Smad3 to mediate renal fibrosis directly via the CD32b-ERK/p38 MAP kinase-crosstalk pathway and indirectly through the TGF-β1-dependent mechanism." (PMID 35541902, 2022). "Results from this study provided evidence for an essential role of Smad3 signalling in the pathogenesis of UUO-induced renal fibrosis and inflammation under high CRP conditions." (PMID 34671208, 2021). "The protection against TGF-β1/Smad3-mediated renal fibrosis and NF-κB-driven renal inflammation are likely mechanisms by which deletion of Smad3 ameliorated kidney injury in CRP Tg mice with UUO." (PMID 34671208, 2021). "We also explored the mechanisms by which Smad3 KO mice were protected against CRP-induced renal fibrosis in vivo and in vitro." (PMID 34671208, 2021). "Next, we examined the effect of Smad3 deletion on CRP-induced renal fibrosis and inflammation in UUO mice." (PMID 34671208, 2021). "We also investigated the functional role of Smad3 in CRP-induced renal fibrosis using Smad3 stable knockdown NRK52E TECs." (PMID 34671208, 2021). "A novel and significant finding in the present study was that CRP mediated renal fibrosis via the CD32b-Smad3-mTOR signaling pathway." (PMID 27221338, 2016). "CRP alone was able to enhance Smad3-mTOR interaction and induce mTOR/S6K activation and renal fibrosis." (PMID 27221338, 2016). "The mechanism whereby CRP promoted renal fibrosis through the CD32b-Smad3-mTOR mechanism was identified in vivo and in vitro." (PMID 27221338, 2016). "The functional importance for the CD32b-Smad3-mTOR pathway in renal fibrosis was further demonstrated by the ability of rapamycin to inactivate the mTOR signaling, thereby inhibiting CRP and high glucose-induced CTGF and collagen I expression." (PMID 27221338, 2016). "Here, we tested a hypothesis that CRP may promote renal fibrosis and inflammation via a TGF-β/Smad3-dependent mechanism." (PMID 34671208, 2021). "Smad3 mediates renal fibrosis by promoting CRP-induced TGF-β1/Smad3 signalling." (PMID 34671208, 2021). "Since CRP mediates renal fibrosis by stimulating TGF-β1 expression, we hypothesized that CRP-induced TGF-β1 expression may be Smad3 dependent." (PMID 34671208, 2021). "CRP may promote CD32b- NF-κB signaling to mediate renal inflammation and may enhance renal fibrosis in T2DN via CD32b-Smad3-mTOR signaling." (PMID 34603198, 2021). "Immunohistochemistry, western blotting, and quantitative real-time PCR revealed that, compared with control UUO mice, CRP Tg/Smad3 WT mice developed severe renal fibrosis by increasing both mRNA and protein levels of collagen I, fibronectin, and α-smooth muscle actin (α-SMA)." (PMID 34671208, 2021). "More work with administration of CRP post AKI is needed to confirm if CRP promotes renal fibrosis." (PMID 28886014, 2017). "CRP may promote renal inflammation via the CD32b-NF-κB signaling mechanism, whereas, CRP may enhance renal fibrosis via the CD32b-Smad3-mTOR signaling pathway." (PMID 27221338, 2016). "CRP may promote CD32b- NF-κB signaling to mediate renal inflammation; whereas, CRP may enhance renal fibrosis in T2DN via CD32b-Smad3-mTOR signaling." (PMID 27221338, 2016).
renal fibrosis (continued). "Finally, we also found that CRP induced renal fibrosis through a CD32b-Smad3-mTOR pathway because blocking mTOR signaling with rapamycin inhibited CRP-induced CTGF and collagen I expression." (PMID 27221338, 2016). "This may also explain why deletion of Smad3 inhibits UUO-induced renal fibrosis in CRP Tg mice." (PMID 34671208, 2021). "Thus, activation of CD32b-Smad3-mTOR signaling may be a key mechanism by which CRP mediates renal fibrosis." (PMID 27221338, 2016). "Reduced expression levels of inflammatory factors such as C-Reactive Protein (CRP) and C-C Motif Chemokine Ligand 2 (CCL2) enhance kidney function, decrease renal fibrosis, and improve inflammation control." (PMID 38362272, 2024). "Blockade of the CRP signaling with an anti-CD32b antibody or Smad3 signaling with a specific inhibitor (SIS3) was able to inhibit mTOR signaling, thereby attenuating renal fibrosis including mesangial expansion under high CRP conditions in vivo and in vitro." (PMID 27221338, 2016). "In this study, we found that mice lacking Smad3 were protected against CRP-exacerbated kidney injury, including progressive renal fibrosis and inflammation." (PMID 34671208, 2021). "In contrast, CRP Tg mice lacking Smad3 (CRP Tg/Smad3 KO) were protected from CRP-exacerbated renal fibrosis by inhibiting expressions of collagen I, fibronectin, and α-SMA mRNA and protein." (PMID 34671208, 2021). "Circulating levels of PTX3 and classical inflammatory mediators, including the clinical prototypical C-reactive protein (CRP), were assessed in 246 ESRD patients on dialysis and analysed in relation to the lipid profile, adipokine levels, and nutritional, cardiac, and renal fibrosis markers." (PMID 31316299, 2019).
spinal tuberculosis (13 papers, 2016 to 2026). "The erythrocyte sedimentation rate (ESR) and C-reactive protein (CRP) have historically been used as biomarkers for spinal tuberculosis." (PMID 36826156, 2023). "A promoter polymorphism in IL-10 (rs1800871) was associated with increased CRP and ESR levels in patients with spinal tuberculosis, a complication of Mycobacterium tuberculosis infection." (PMID 37238156, 2023). "CRP is as high as 41.9 mg/L before surgery for severe spinal tuberculosis and ESR is as high as 51.4 mm/h." (PMID 35633888, 2022). "Our research showed that ESR and CRP had little contribution to the diagnosis of spinal tuberculosis and the severity of the disease." (PMID 35633888, 2022). "This study aimed to investigate the expression of TNFα and CRP in Tuberculous Spondylitis (TB) and its relationship with instrumentation." (PMID 34815862, 2021). "Patients with pyogenic spondylitis showed significantly higher serum erythrocyte sedimentation rate, C-reactive protein, and procalcitonin levels than those with tuberculous spondylitis." (PMID 30177857, 2018). "Our study also confirmed the inability to differentiate spinal tuberculosis from other diseases on the basis of ESR, CRP, and WBC." (PMID 36204647, 2022). "Notably, our results show that localized streptomycin irrigation given to the lesion during surgical procedures for spinal tuberculosis effectively reduced the patient's postoperative ESR and CRP levels (both p-values < 0.05)." (PMID 37563683, 2023). "Here, we report a case of spinal tuberculosis without elevation of C-reactive protein (CRP) at the initial visit mimicking spinal metastasis." (PMID 32908752, 2020).